CD4 (CD4 molecule)
Diseases named in the same sentence as CD4 in open-access papers (continued):
Sharing a sentence is not in itself a finding about the gene and the disease.
viral infection (continued). "HIV destroys CD4+ T-cells and significantly reduces a human's resistance to viral infectious diseases as well as severe bacterial infections, which can lead to certain illnesses." (PMID 36404912, 2022). "Another study found T CD4 lymphocytes from previous influenza viruses were capable of mitigating other viral infections." (PMID 36362500, 2022). "As Th1/Th17 responses are known to play important roles in the outcome of viral infections, we quantified IL-17+ and IFNɣ+ CD4+ and IFNɣ+ CD8+ lymphocytes in lung tissue after IN and IM vaccination." (PMID 36031930, 2022). "Herein, we demonstrate that CD4 T cells responding to chronic viral infection are more heterogeneous than previously appreciated, with several transcriptionally distinct subsets arising during the early phase of chronic infection." (PMID 36255051, 2022). "Upon acute viral infection, virus-specific CD4+ T cells differentiate into either TH1 cells or follicular helper T (TFH) cells." (PMID 35909969, 2022). "Based on these biological features, CD4 T cells can provide strength to fight against acute and chronic viral infections." (PMID 36324819, 2022). "It will, therefore, be interesting to explore the roles of AaVA-1, D7 (AAEL006417), and NeST1 binding with CD4 in viral infection." (PMID 36070318, 2022). "A report demonstrated that TRAIL+ NK cells control CD4+ T cell responses in the SGs during chronic viral infection to limit autoimmunity." (PMID 36388880, 2022). "A consensus is that virus-specific memory CD4+ T cells are progenies of corresponding effector CD4+ T cells, the so-called memory precursors generated during effector phase of acute viral infection." (PMID 35909969, 2022). "Although we expected to see highly variable V-J gene pairings similar to what we previously observed in CD4 T cells in the setting of acute viral infection, we found different trends between IGRP206-214–reactive and –nonreactive CD8 T cells." (PMID 35667687, 2022). "Yet, we do not fully understand the extent by which the TCR repertoire impacts the early fate decision of CD4+ T cells responding to acute and chronic viral infections." (PMID 35829695, 2022). "IFN‐I can activate the STAT3/4‐granzyme B pathway in tumor‐infiltrating CD8+ T cells, inhibit tumor growth, and directly maintain the clonal expansion of CD4 T cells to fight virus infection." (PMID 35253368, 2022). "In other viral infections, such as HCV, viral persistence is associated with an impaired and fading CD4+ T-cell response that can only be fully recovered through early therapy initiation." (PMID 35746736, 2022). "CD4+ T cells are an important component of adaptive immunity in the control of viral infections such as SARS-CoV-2." (PMID 35935575, 2022). "Several different phenotypes of cytotoxic CD4+ T cells have been described and are considered to add protection during viral infections and cancer." (PMID 36447264, 2022). "Following viral infections, naive CD4+ T cells clonally expand and differentiate into effector populations supporting both cellular and humoral responses." (PMID 35829695, 2022). "CD4+ T cells have many different functions during viral infections, but they are best known for providing help to CD8+ T cells and B cells, as well as for recruitment of immune cells via the secretion of cytokines." (PMID 35215790, 2022). "SERPINA1 directly interacts with the gp41 protein of HIV and thus inhibits its binding to the host CD4 co-receptor; thereby, inhibiting viral infection." (PMID 36159797, 2022). "During acute viral infections, regulatory T lymphocytes (Tregs), a subpopulation of T cells (FoxP3+ CD4+CD25+), play an essential role in controlling inflammation and preventing autoimmunity and tissue complications by regulating immune system homeostasis." (PMID 35887067, 2022). "CD4 T cells responding to chronic viral infection display altered subset distribution patterns and core gene expression modules compared to their acute infection counterparts." (PMID 36255051, 2022).
viral infection (continued). "likewise showed that Herpes virus 6 viremia was associated with impaired T cell immune reconstitution in children after HSCT due to the viral infection of CD4+ T cells." (PMID 36211398, 2022). "DIVA not only boosts CTL responses that are important in many viral infections and tumor specific immunity but also primes specific CD4+ T cell responses with a Th1 type cytokine profile that also support cell-mediated cancer immunity." (PMID 36153349, 2022). "CD4 + helper T cells improve immune response against viral infection by secreting immune-stimulatory cytokines to elevate CD8 + T lymphocytes’ cytotoxic activity, and B cells specific neutralizing antibody secretion." (PMID 35842705, 2022). "Such CD4+ cytotoxic function is also found insome other viral infections.Cytotoxic CD4+ T-cell characteristics are primarily found by EM cells ratherthan CM cells." (PMID 36865570, 2022). "Accumulating evidence suggests that abnormal expression of Tim-3 on peripheral CD4+ and CD8+ T cells is closely associated with autoimmune diseases, viral infections, and cancers." (PMID 36186992, 2022). "Cellular immunity plays an influential role against viral infections, activating CD4+ T-cells, CD8+ T-cells and B-cells." (PMID 36423113, 2022). "T13, the Tregs (CD25+FOXP3+CD45RO+CD4+), is essential to maintain immune homeostasis via governing aggravated and destructive inflammation, exhibiting protective roles in the host during viral infections." (PMID 35720399, 2022). "Several recent studies have identified that CD4+ T cells responding to acute viral infection are composed of multiple transcriptionally distinct CD4+ T cell subsets, including Th1, Tfh, and Tcmp cells." (PMID 36255051, 2022). "NK cell-derived IFN-γ can directly induce CD4+ T cell differentiation into type I T helper cells, facilitating the control of bacterial or virus infection." (PMID 35439922, 2022). "Further, CD4+ T cells also exert direct cytotoxicity through granzyme B and perforin release during viral infections." (PMID 36591284, 2022). "In acute viral infection or vaccination, a small proportion of the antigen-experienced CD4+ T cells survive after antigen clearance, subsequently become the memory CD4+ helper T cells." (PMID 35909969, 2022). "During viral infection, virus-specific CD4+ T cells mainly differentiate into T helper type 1 (TH1) cells and follicular helper T (TFH) cells." (PMID 35909969, 2022). "Similar trends were observed in CD8+ and CD4+ T cells isolated from perfused lung tissue, an important site for resident T cell immunity to facilitate early detection and mediation of nascent viral infection." (PMID 36307453, 2022). "In viral infections, SARS-CoV-2, hCoV-229E, or HIV activate Panx1 hemichannels via CD4/CXCR4 CD4/CCR5, causing an outflow of ATP, which induces the maturation of IL-1ß through the activation of P2X7 receptors." (PMID 36699007, 2022). "CD4+ T cells are activated via the secretion of Th2-related cytokines (IL-4, IL-5) to stimulate B cells for the production of antibodies to prevent viral infection." (PMID 35632667, 2022). "B cells secret antibodies to block virus infection, CD4+ T cell helps B cells to proliferate and produce antibodies, while cytotoxic T cells function to kill virus-infected cells." (PMID 35107382, 2022). "Currently, it has been confirmed that CD4+ T cells exhibited a skewed differentiation toward follicular helper T cells during chronic viral infection, which has been induced by type I interferon." (PMID 35784297, 2022). "Studies employing major histocompatibility complex (MHC) class I tetramers in mice and humans have demonstrated that during the activation phase, about 50% of CD8+ T cells and about 10% of CD4+ T cells respond to a viral infection leading to mass expansion." (PMID 36560733, 2022). "While the role of cytotoxic CD4 T-cells is still unclear, the presence of these cells has been described in several viral infections." (PMID 34140294, 2022).
viral infection (continued). "T cells play a central role in many viral infections, among which CD4+ T cells mediate B cell help for antibody production and coordinate the response of other immune cells types, including CD8+ T cell lysis of infected cells." (PMID 35336918, 2022). "The adaptive immune system is critical to the clearance of all viral infections and the interactions of the adaptive immune cell components made up of B cells, CD4+ T cells, and CD8+ T cells are essential for immune protection." (PMID 35632512, 2022). "Vaccination with rAb ZH9F7-Cap promotes the differentiation of CD4+ CD8+ IFN-γ-secreting cells since these populations have strong antiviral activity against other populations of viral infections pigs." (PMID 35632440, 2022). "In conclusion, we utilized a model of chronic viral infection to evaluate the efficacy of adoptive B cell therapy, and we demonstrate that it can help control a persistent viral infection, especially if combined with CD4 T cell therapy." (PMID 35958615, 2022). "During viral infection, B cells function as antigen-presenting cells by presenting viral peptides to CD4 + cells through MHC-II38." (PMID 36371522, 2022). "The previous study showed that CRISPR/Cas9 targeting CXCR4 or CCR5 chemokine receptors, the co-receptors for HIV-1, protected the primary CD4+ T cells from viral infection." (PMID 36499376, 2022). "In the course of viral infection, Th2 CD4+ T cells promote the humoral immune response by secreting IL-4, IL-5, IL-10 and other Th2 cytokines." (PMID 35100303, 2022). "IL-17 producing CD4+ T cells have been reported in other bacterial and viral infections such as tubercle bacillus, leishmaniasis, and HIV and present pathogenesis in the experimental models of autoimmune diseases." (PMID 36389696, 2022). "During viral infections and tumorigenesis, effector CD4+ and CD8+ T cells act as master players of the adaptive immune system to eradicate the virus and tumor cells from the host." (PMID 36268018, 2022). "In this study, we found that CS exposure or viral infection alone caused the recruitment of immune cells, as demonstrated by the increased Ly6G, CD3+CD8+, and decreased CD3+CD4+." (PMID 36269393, 2022). "After acute viral infections, pathogen clearance is followed by the persistence of memory CD4+ T cell populations that acquire distinct phenotypes, gene expression and functional properties." (PMID 35829695, 2022). "Although CD4+ T cells are critical for promoting and sustaining CD8+ T cell responses during chronic viral infection, recent research has revealed more definite roles of CD4+ T in anti-tumor immunity." (PMID 35784297, 2022). "During viral infection, the orchestration of CD4+ T cells, CD8+ T cells and B cells constitutes the core events of host adaptive immunity, which confers specialized and long-term cellular and humoral immune protection." (PMID 35909969, 2022). "It has been reported that during viral infections CD4+ T cells expressing perforin can play either a protective and/or pathogenic role." (PMID 35336918, 2022). "Both classes, MHC-I and MHC-II, are restricted to CD8+ cytotoxic T-lymphocytes (CTLs) and CD4+ helper T-lymphocytes, respectively, and both play a vital role in viral infections." (PMID 35746477, 2022). "Mice receiving combined CD4 and CD8 T cell depletion or CD4 T cell depletion alone showed high systemic viral infection in the kidney, spleen, and brain." (PMID 36341713, 2022). "Together, these data indicate that Cavβ1 is required for the clonal expansion of CD4+ T cells in vitro and in vivo after viral infection by regulating T cell survival." (PMID 35440113, 2022). "Limited IL-2 production by CD4+ T cells is detrimental to the adaptive immune response as this cytokine is critical for sustaining CD8+ T cells during viral infection." (PMID 35774790, 2022).
viral infection (continued). "It remains to be confirmed if the kinetics of CD4 CTL triggering in events such as re-activation of persistent viral infections, or autoimmune flare-ups, are similarly delayed compared to CD8+ effector activation." (PMID 35903098, 2022). "An in vitro study examining HCV infected human hepatocytes co-cultured with CD4+ T cells showed that the CD4+ T cells had increased expression of galectin-9, TGFβ and IL-10, indicating viral infection was driving regulatory phenotypes." (PMID 36032131, 2022). "The PCR results from blood during the different hospital admissions show decreasing viral load over the three episodes, probably due to improved specific immunity by a CD4+ cell-mediated booster effect as known from other viral infections." (PMID 35752863, 2022). "Of note, CD4 T cells with cytotoxic functions have also been described, initially in viral infections, autoimmune disorders and more recently also in cancer settings." (PMID 35572552, 2022). "A robust CD4 T cell response is needed to activate B cells that transform into plasma cells and plasmablast, which produce specific antibodies to fight viral infection." (PMID 35265078, 2022). "An increasing number of studies have confirmed that the antigenic load during viral infections directly contributes to CD4+ and CD8+ T cell exhaustion, and several ncRNAs have been identified to be involved." (PMID 36268018, 2022). "Both Th1 cells and T-follicular helper cells are produced via CD4+ T-cell differentiation after virus infection." (PMID 35632512, 2022). "In contrast to viral infection, in tumor-draining LN we observed a sizable fraction (~10%) of Treg among antigen-specific CD4+ T cells." (PMID 35829695, 2022). "Elimination of a viral infection requires the interaction of various immune cell types including CD4+ T cells, CD8+ T cells, B cells NK cells and monocytes." (PMID 35898494, 2022). "WT infected patients also showed higher IL-17+ CD4+ T cells but with lower IL-4+/IL-6+ CD4+ T cells compared to patients with mutant virus infection." (PMID 34716845, 2022). "As known, CD4+ T cell help is indispensable for sustaining CD8+ T cell function during chronic viral infection and engaged in anti-tumor activities by CD8+ cytotoxic T cells-dependent apoptosis." (PMID 35562682, 2022). "Antagonizing C5aR led to a decline in TNTs in DC culture as well as in DC/CD4+ T-cell co-cultures accompanied by a reduction in viral infection and local C3 production by DCs." (PMID 35204813, 2022). "When a viral infection occurs, the immune system induces naive CD4 T cells to actively differentiate into two lineages: Th1 cells and Tfh cells." (PMID 35983065, 2022). "Studies on virus infection in goats have shown that specific CD4+ T cells are the main mediators of protection against viral infection." (PMID 35513847, 2022). "Infection-induced tumor-specific memory CD4+ T cells can prevent lung metastasis, inferring that the vaccine to prevent virus infection can also protect the host from tumorigenesis." (PMID 35784297, 2022). "Collectively, these observations suggest CD101-expressing cells represent a functionally distinct population of CD4 T cells that can play a key role in regulating inflammatory environments, such as those after a viral infection." (PMID 35867722, 2022). "This study also provides a potential strategy to restore impairment in mtDNA topology as a means to improve CD4 T cell functions during human viral diseases." (PMID 36405960, 2022). "Poly(I:C) also increases cytotoxic activity in CD4+ T lymphocytes in viral infections, promoting adaptive immune response." (PMID 35625619, 2022). "Meanwhile, IFI6, IFITM2, ISG15, and LDHB were highly expressed in memory CD4+T cells, which were crucial for cell hypermetabolism and defense against virus infection." (PMID 35095832, 2021). "In fact, a subpopulation of CD4+ TRM cells promotes humoral responses in the lung after viral infection." (PMID 33968018, 2021).
viral infection (continued). "In comparison with the non-infectious patients, significant increase of CD8+ cell population and decrease of CD4/CD8 ratio in AH during the acute phase of viral infection were observed in the viral infectious patients." (PMID 33933004, 2021). "HIV-1 RNA contains m6A modifications that modulate viral infection and gene expression in CD4+ T cells." (PMID 33690734, 2021). "These CD4 TEMRA cells are more frequent in patients with some viral infections, such as dengue virus or cytomegalovirus, and they show a decreased CD27 expression but an increased expression of effector molecules." (PMID 33572562, 2021). "Studies of non–Sub-Saharan African cohorts show that CD4+ T cells within the large intestinal mucosa are major sites for viral infection and replication even during plasma viral suppression." (PMID 34618690, 2021). "Our in-silico results in asthmatic blood showed that KRT8 mRNA expression was higher in CD8 T lymphocytes in contrast to CD4 T lymphocytes and upregulated significantly in asthmatic who develop cold symptoms due to viral infection." (PMID 34088958, 2021). "In viral infections, these perforin expressing CD4 T cells have been shown to play a protective and/or pathogenic role." (PMID 33777054, 2021). "Antibody responses are closely correlated with CD4+T cell subsets that play important roles in the control of viral infections, including T helper (Th) 1 (Th1), Th2, and Th17 cells and follicular helper T (Tfh) cells." (PMID 34603308, 2021). "CD4+ T cells play a vital role in the control of many viral infections by generating neutralizing antibodies and priming of CD8+ T cells." (PMID 34322120, 2021). "In persistent viral infection in the brain, provision of IL-21 by T follicular-like tissue-resident CD4 T cells likely promotes ATP production in local CD8 T cells through enhancing electron transport chain efficiency." (PMID 33854506, 2021). "During viral infection, CD4+ T cells can provide effective immunity protection through direct effector function and by helping other leukocytes to maximize the protective activities." (PMID 34127062, 2021). "The presence and characteristics of CD4+ cytotoxic T lymphocytes (CTLs) have been described for murine or human viral infection." (PMID 34853796, 2021). "Preimmunization of SJL mice with capsid-epitope peptides significantly increased capsid-specific CD4+ T cell numbers in the CNS during the early stages of viral infection." (PMID 34067536, 2021). "We detected specific CD4 T cell responses against SARS-CoV-2 that localized to the lung 21 days after viral infection." (PMID 34929014, 2021). "The direct cytotoxic function of CD4+ T cells has been confirmed in several models of viral infections, and shown to depend tightly on TCR signal strength." (PMID 33430234, 2021). "During viral infectious diseases, the involvement of CD4+CD25+ Tregs in immune regulation is one of the important reasons for chronic infection and immune escape of virus." (PMID 34526112, 2021). "Post-mortem studies on brain tissue from HIV-affected patients are suggestive of the presence of viral DNA and viral proteins in the astrocytes that lack CD4 expression, thereby highlighting a CD4-independent mechanism of virus infection." (PMID 34452054, 2021). "CD4+ CTLs have been most commonly identified in the context of viral infection or antitumor immunity and appear to be closely related to Th1 cells." (PMID 34403374, 2021). "When responding to viral infection, the CD4+ T cells mainly have a Th1-type phenotype expressing T-bet and produce large amounts of IFNγ." (PMID 34127062, 2021). "Regarding HIV-1, DC-SIGN binds to the highly glycosylated HIV envelope (Env) gp120 in a CD4-independent fashion and can efficiently transfer the virus to CD4+ permissive T cells, thereby facilitating viral infection in trans." (PMID 33451024, 2021).